SYK (spleen associated tyrosine kinase)
Diseases named in the same sentence as SYK in open-access papers (continued):
Sharing a sentence is not in itself a finding about the gene and the disease.
Ewing sarcoma (4 papers, 2018 to 2024). A small round cell tumor that lacks morphologic, immunohistochemical, and electron microscopic evidence of neuroectodermal differentiation. "Interestingly, c-MYC was also reported to transcriptionally activated MALAT1 by binding to MALAT1 promoter, which contributes to a novel SYK/c-MYC/MALAT1 pathway to promote Ewing Sarcoma." (PMID 30683916, 2019). "A link between SYK and MYC has been previously demonstrated in Ewing sarcoma and hematopoietic cells." (PMID 30744170, 2019). "ERK- and Akt-mediated signaling is known to be affected by SYK inhibition in CLL and Ewing sarcoma." (PMID 30744170, 2019). "In Ewing sarcoma (EWS), a devastating soft tissue sarcoma affecting predominantly young individuals, MALAT1 was identified to be transcriptionally upregulated through a SYK/c-MYC axis, and to positively mediate SYK tyrosine kinase oncogenic activity." (PMID 29739426, 2018).
gastric cancer (4 papers, 2013 to 2024). A primary or metastatic malignant neoplasm involving the stomach. "The hypermethylation of the SYK promoter was positively correlated with tumorigenesis and metastasis in gastric cancer, highly indicating that SYK is a potential tumor suppressor in gastric cancer." (PMID 36979962, 2023). "SYK over-expression has been described in other solid tumors, such as breast and gastric cancer, and seems to correlate with improved prognosis and reduced invasion." (PMID 24278200, 2013). "Finally, five proteins, including NDRG1_pT346, SYK, P90RSK, TIGAR, and XBP1, were related to the risk prognosis of gastric cancer and were selected for model construction." (PMID 36979962, 2023). "CLEC-2 prevents the activation of Ser and Thr kinase (AKT) and glycogen synthase kinase 3β (GSK3β) signaling in a spleen tyrosine kinase (SYK)-dependent manner, as well as the invasiveness and expression of EMT markers in cancer cell lines, which suppressed gastric cancer cell metastasis." (PMID 39517244, 2024).
inflammatory bowel disease (4 papers, 2018 to 2023). A spectrum of small and large bowel inflammatory diseases of unknown etiology. "We will also focus on the critical role of SYK in airway inflammation, fibrosis, inflammatory bowel disease (IBD), inflammatory skin disease and neuroinflammation." (PMID 37506139, 2023).
liver disease (4 papers, 2018 to 2022). "In this review, we mainly provide a general overview of the function and significance of SYK in the development of different liver diseases, and discuss the opportunities of SYK inhibition as novel therapeutic approach for liver disease treatment." (PMID 36568669, 2022). "So far, a variety of mouse-based experimental models have revealed the intricate roles and mechanisms of SYK in liver diseases." (PMID 34853322, 2021). "All the results suggest that myeloid SYK seems to be a very potential target for the treatment of liver disease." (PMID 34853322, 2021). "In liver diseases, SYK contributes to the development of alcoholic liver disease and liver fibrosis, suggesting that SYK can be a potential therapeutic target for liver diseases." (PMID 31780731, 2019). "Especially, some studies have indicated that the splenic lymphocytes can migrate into liver, and regulate the development of liver disease, in which SYK may also play an important position." (PMID 36568669, 2022). "Spleen tyrosine kinase (SYK); Liver diseases; Small molecule inhibitor; Therapy target." (PMID 36568669, 2022). "Totally, even though some critical points about the significance of SYK in liver diseases treatment still need further elaboration, more reliable biotechnical or pharmacological therapy modes will be established based on the better understanding of the relationship between SYK and liver diseases." (PMID 36568669, 2022). "In this review, we mainly summary the role of SYK in different liver diseases." (PMID 36568669, 2022). "Thus, the current studies highlight SYK as a promising therapeutic target in the treatment of liver diseases." (PMID 36568669, 2022). "Studies have shown that the use of SYK kinase inhibitors to block SYK phosphorylation can effectively reduce the development of various liver diseases, including liver fibrosis, alcoholic liver disease, non-alcoholic fatty liver, hepatocellular carcinoma." (PMID 34853322, 2021). "Therefore, the non-hepatic SYK, such as the SYK in spleen monocytes, could be an important therapeutic target for liver diseases, and the therapeutic action of splenectomy against liver diseases may be also relevant with the inhibition of non-hepatic SYK." (PMID 36568669, 2022). "In addition, the blockage of SYK activity using small molecule modulators is considered as a significant therapeutic strategy against liver diseases, and both hepatic SYK and non-hepatic SYK could become highly promising therapeutic targets." (PMID 36568669, 2022).
osteoarthritis (4 papers, 2012 to 2021). A noninflammatory degenerative joint disease occurring chiefly in older persons, characterized by degeneration of the articular cartilage, hypertrophy of bone at the margins and changes in the synovial membrane. "Both the total and phosphorylated forms of SYK are expressed in increased levels in RA synovial tissues compared with osteoarthritis, and SYK inhibition reduced the expression of IL-6 and MMP-3." (PMID 23249408, 2012). "Thus, SYK inhibition may have therapeutic potential in the vasculature and perhaps also at other locations where CaP particles appear to be damaging, such as in osteoarthritis." (PMID 29274344, 2018).
prostate carcinoma (4 papers, 2017 to 2019). A carcinoma that arises from epithelial cells of the prostate gland. "SYK is upregulated in human prostate cancer and is associated with malignant progression." (PMID 29372378, 2018). "SYK was found to be upregulated in human prostate cancer and associated with malignant progression." (PMID 29376139, 2017). "The studies in prostate cancer reported that SYK supports migration and growth of prostate cancer cells." (PMID 29719615, 2018). "For instance, Ghotra and colleagues have identified SYK as a candidate kinase target for the treatment of advanced prostate cancer." (PMID 29376139, 2017).
schizophrenia (4 papers, 2011 to 2025). A major psychotic disorder characterized by abnormalities in the perception or expression of reality. "In summary, the SIRPB1 mediated LCK and SYK gene activation are associated with schizophrenia related to BA22 tissue specific gene." (PMID 24564241, 2013). "The results help to explain that the over-expression genes SIRPB1, LCK and SYK are responsible for one of the possible disease mechanisms for schizophrenia." (PMID 24564241, 2013). "SYK and LCK were the over-expression genes with high betweenness, however, SIRPB1 was an over-expressed gene for schizophrenia and directly linked to SYK from the QQPPI of SHCN, and it may have an implication of a potential disease mechanism for schizophrenia." (PMID 24564241, 2013). "Notable examples include SYK for AD and THRB for schizophrenia." (PMID 40502754, 2025). "Another responsible pathway involves the IL-2 pathway which Interleukin-2 binds to the IL-2 receptor to activate LCK and SYK, which helps explain that the over-expression genes: SIRPB1, LCK and SYK might be responsible for one of the possible disease mechanisms for schizophrenia." (PMID 24564241, 2013). "For example, the over-expressing schizophrenia candidate genes, SIRPB1, SYK and LCK, are responsible for signal transduction in cytokine production; immune responses involving IL-2 and TREM-1/DAP12 pathways are relevant for the etiology mechanism of schizophrenia." (PMID 24564241, 2013).
acute kidney injury (3 papers, 2023 to 2025). Sudden and sustained deterioration of the kidney function characterized by decreased glomerular filtration rate, increased serum creatinine or oliguria. "SYK signaling pathway plays a key role in DCs and neutrophils during sepsis‐induced acute kidney injury." (PMID 37506139, 2023).
alcoholic liver diseases (3 papers, 2019 to 2024). A disorder caused by damage to the liver parenchyma due to alcohol consumption. "Furthermore, previous studies have found that binge drinking can induce SYK activation, and pharmacological inhibition of SYK significantly decreases alcoholic liver disease in a mouse model of binge drinking." (PMID 38633406, 2024).
allergies (3 papers, 2011 to 2019). "SYK is reported to be a tumor suppressor gene and its expressional abnormality is also associated with various allergies." (PMID 31531378, 2019).
B-cell acute lymphoblastic leukemia (3 papers, 2017 to 2020). A neoplasm of lymphoblasts committed to the B-cell lineage, typically composed of small to medium-sized blast cells. "A recent study in precursor B-cell acute lymphoblastic leukemia revealed that pre-BCR signaling regulates PI3K/AKT, FOXO1 and MYC and can be a target of SYK inhibition." (PMID 28212447, 2017).
diabetes (3 papers, 2024 to 2026). "To explore the underlying role of SYK in diabetes-induced senescence of the vascular smooth muscle layer, we utilized the SYK-specific inhibitor R406 in diabetic mice and VSMCs to block the SYK pathway." (PMID 38733164, 2024). "The data support an essential role for Müller glial SYK in diabetes-induced retinal inflammation and the development of functional deficits in vision." (PMID 41972434, 2026). "This study investigated the role of Müller glial spleen tyrosine kinase (SYK) in diabetes-induced retinal complications." (PMID 41972434, 2026). "Müller glia-specific SYK deletion also prevented diabetes-induced retinal thinning and visual function deficits in spatial frequency threshold and contrast sensitivity." (PMID 41972434, 2026).
glioblastoma (3 papers, 2014 to 2025). The most malignant astrocytic tumor (WHO grade IV). "By using deconvolution microscopy and high-resolution confocal laser scanning microscopy, we first examined the subcellular localization of GFP-tagged recombinant SYK protein in the U373 human glioblastoma cell line that was stably transfected with the eukaryotic SYK expression vector pEGFP-SYK." (PMID 25506060, 2014). "Our findings highlight the importance of stromal heterogeneity in glioblastoma and suggest that targeting CAF-related signaling, including SYK, may offer new therapeutic opportunities for this lethal disease." (PMID 41463192, 2025).
glomerulonephritis (3 papers, 2018 to 2021). A renal disorder characterized by damage in the glomeruli. "This suggests that SYK inhibition may be an effective treatment in more inflammatory forms of glomerulonephritis, such as ANCA-associated glomerulonephritis, and our findings in this preclinical model suggest that this approach should be tested in clinical studies of AAV." (PMID 32305129, 2020). "SYK inhibition decreased in vitro ANCA-induced cellular responses and attenuated the severity of glomerulonephritis." (PMID 33916214, 2021).
Hypercholesterolemia (3 papers, 2013 to 2023). An increased concentration of cholesterol in the blood. "Thus, inhibition of hypercholesterolemia-associated monocytosis, monocyte infiltration, and differentiation by SYK antagonism attenuates early atherogenesis but not established disease when local macrophage proliferation dominates lesion progression." (PMID 26891724, 2016). "The network in the MCA with largest number of up-regulated focus genes affected by hypertension plus hypercholesterolemia showed many molecules related to ERK 1/2, interferon alpha, IL12, SYK, CD2, CD4, and CD244." (PMID 23874591, 2013).
Hypertension (3 papers, 2013 to 2025). The presence of chronic increased pressure in the systemic arterial system. "However, fostamatinib's action is not exclusive to SYK and inhibits other kinases, such as VEGFR, in an off‐target manner, leading to the development of arterial hypertension." (PMID 40962713, 2025).
injury (3 papers, 2023 to 2025). Damage inflicted on the body as the direct or indirect result of an external force, with or without disruption of structural continuity. "Mice with SYK-deficient myeloid cells display a similar phenotype to those treated with pharmacologic inhibitors, suggesting the SYK exerts the majority of its effects in leukocytes during kidney injury." (PMID 40857403, 2025).
invasive breast carcinoma (3 papers, 2014 to 2021). A carcinoma that infiltrates the breast parenchyma. "The SYK promoter is methylated in invasive breast cancers; and, methylation values were correlated with reduction in SYK mRNA levels in immune depleted cases; similarly protein levels were positively associated with SYK mRNA levels." (PMID 24523870, 2014). "It was inferred that SYK loss might contribute to the development of invasive breast cancer." (PMID 24523870, 2014).
liver cancer (3 papers, 2021 to 2024). An epithelial or non-epithelial malignant neoplasm that arises from the liver. "GS-9973, as a specific small molecule inhibitor of SYK, may provide additional benefits for patients with liver cancer." (PMID 39261768, 2024). "GS-9973 reduced NETs formation by inhibiting the SYK/PKM2/P-STAT3 pathway in neutrophils and the NLRP3 inflammasome pathway dependent on IL-1β in macrophages, thereby alleviating hepatic IRI and liver cancer recurrence." (PMID 39261768, 2024). "Although SYK is widely expressed in parenchymal and non-parenchymal cells of the liver, which has also been verified by us (date not show), two new inhibitors, PRT062607 and Piceatannol, have been studied in myeloid cells to reveal their protective effects on liver fibrosis and liver cancer in vivo." (PMID 34853322, 2021).
lupus nephritis (3 papers, 2017 to 2023). Glomerulonephritis in the context of systemic lupus erythematosus. "SYK, BTK, PDGFR, EFGR, DDR1 and Janus kinase are implicated in the pathogenesis of lupus nephritis." (PMID 28391340, 2017).
myeloproliferative neoplasm (3 papers, 2020 to 2025). A clonal hematopoietic stem cell disorder, characterized by proliferation in the bone marrow of one or more of the myeloid (i.e., granulocytic, erythroid, megakaryocytic, and mast cell) lineages. "SYK is indispensable for myeloproliferative disease development and its transformation to AML and a critical regulator of FLT3-ITD driven neoplasia due to its role in FLT3 transactivation." (PMID 31992353, 2020). "Moreover, patients with an unclassified myeloproliferative neoplasm harboring PML-SYK gene fusion show an upregulation of phospho-SYK, phospho-STAT5, phospho-ERK1/2, and phospho-S6 genes that drives a hyperactivated signal modulated by the epichaperome." (PMID 39936995, 2025).
Obesity (3 papers, 2021 to 2025). Accumulation of substantial excess body fat. "Notably, our data-based in silico predictions suggest the potential of repurposing the SYK inhibitor fostamatinib for obesity treatment in relevant genetic profiles." (PMID 38281958, 2024). "Notably, FCER1G, LYN and SYK downregulation were able to reduce obesity induced by high-fat diet and the growth of lipid droplets in adipocytes." (PMID 34506234, 2021).
peripheral T-cell lymphomas (3 papers, 2016 to 2023). "ITK-SYK, which results from the fusion between SYK and ITK (IL-2-inducible T-cell kinase), occurs as a recurrent translocation in 17% of patients with unspecified peripheral T-cell lymphomas." (PMID 28881711, 2017). "Among mature T-cell neoplasms, subsets of Peripheral T-cell Lymphomas, not otherwise specified (PTCL, NOS) and Angioimmunoblastic T-cell Lymphomas (AITL) display SYK translocations and ITK-SYK fusion proteins." (PMID 26943776, 2016).
psoriasis (3 papers, 2020 to 2023). An autoimmune condition characterized by red, well-delineated plaques with silvery scales that are usually on the extensor surfaces and scalp. "The JAK/STAT signaling and spleen tyrosine kinase (SYK) pathways are implicated in numerous autoimmune and inflammatory diseases (e.g. AD, psoriasis, alopecia areata), modulating a range of immune responses, including the Th2 (IL-4, IL-13, CCL18), Th1 (IFNγ), and Th17/Th22 (CCL20, S100As) pathways." (PMID 33329590, 2020).
pulmonary fibrosis (3 papers, 2022 to 2026). Chronic progressive interstitial lung disorder characterized by the replacement of the lung tissue by connective tissue, leading to progressive dyspnea, respiratory failure, or right heart failure. "Collectively, these results suggest that ERBB4 and SYK are attractive targets for IPF treatment; however, further preclinical studies are needed to confirm the suppression of lung fibrosis following the inhibition of the expression and activation of these kinases." (PMID 35130915, 2022).
small cell lung carcinoma (3 papers, 2013 to 2017). Small cell lung cancer (SCLC) is a highly aggressive malignant neoplasm, accounting for 10-15% of lung cancer cases, characterized byrapid growth, and early metastasis. "It is noteworthy that SYK, an oncogenic kinase and a potential therapeutic target for Small-cell lung cancer and hematologic neoplasms, was over-expressed in subtype I." (PMID 28178664, 2017). "WGCNA identifies Spleen Tyrosine Kinase (SYK) as a candidate oncogene in a subset of small-cell lung cancer." (PMID 26944061, 2016).
steatosis (3 papers, 2019 to 2021). Increased lipid within the cytoplasm of cells. "It was also reported that induction of proinflammatory cytokine and hepatocyte steatosis is also conciliated by the spleen tyrosine kinase (SYK) activation in inflammatory hepatic hepatocytes and mononuclear cells in mice treated with chronic alcohol." (PMID 34064981, 2021). "Inhibition of SYK could ameliorate the inflammation and steatosis of NAFLD by reducing the activation of macrophages and the production of CCl2, IL-6 and TNF-α." (PMID 34506234, 2021).
tauopathy (3 papers, 2020 to 2025). Neurodegenerative disorders involving deposition of abnormal tau protein isoforms (tau proteins) in neurons and glial cells in the brain. "Our analysis revealed a progressive activation of the Clec7a–SYK signaling axis in the hippocampus of PS19 tauopathy mice, correlating with disease progression." (PMID 40243488, 2025). "The SYK inhibitory properties of nilvadipine have been previously demonstrated in mouse models of AD and tauopathies, but more work is required to confirm that this is the mechanism through which it elicits the favorable responses described in this study." (PMID 33076989, 2020). "To explore the role of Clec7a in the PS19 mouse model of tauopathy, we assessed the expression of Clec7a and phosphorylated SYK (p-SYK) in the ventral hippocampus (vHPC), dorsal hippocampus (dHPC), and cortex of PS19 mice and their wild-type (WT) littermates at 3, 6, 9, and 12 months." (PMID 40243488, 2025).
virus infection (3 papers, 2015 to 2022). "However, the NS5A protein of HCV also can strongly interact with SYK and suppress the kinase activity, indicating the multiple relationships between virus infection and SYK activation." (PMID 36568669, 2022).
acute leukemia (2 papers, 2022 to 2025). A clonal (malignant) hematopoietic disorder with an acute onset, affecting the bone marrow and the peripheral blood. "Trials have shown promising clinical activity of the selective SYK inhibitor entospletinib in patients with high expressing HOXA9/MEIS1 acute leukemias." (PMID 40188268, 2025). "Additional insights from the present study relate to the upregulation of SYK and JAK expression in pediatric and adult KMT2A/MLL-R+ acute leukemias." (PMID 36627892, 2022). "The availability of FDA-approved potent inhibitors of SYK and JAK provides the opportunity to evaluate their clinical efficacy in KMT2A/MLL-R+ acute leukemias with overexpression of their respective targets." (PMID 36627892, 2022).
allergic asthma (2 papers, 2014 to 2023). A asthma with a basis in a pathological type I hypersensitivity reaction. "The spleen tyrosine kinase, SYK, is a non-receptor tyrosine kinase which plays a key role in IgE-mediated responses in allergic asthma and rhinitis." (PMID 25541997, 2014).